BMP4 (bone morphogenetic protein 4)
Diseases named in the same sentence as BMP4 in open-access papers (continued):
Sharing a sentence is not in itself a finding about the gene and the disease.
cancer (continued). "We then addressed whether cancer cell-derived EVs promoted NSCLC cell growth by regulating the Smad9/BMP4 pathway and thus, CCK-8 proliferation assay and colony formation assay were performed." (PMID 33472665, 2021). "Given that the expression of BMP4 affects the biological behavior of tumors, the change in BMP4 quantity in ascrotal mammals might increase cancer inhibition." (PMID 34702182, 2021). "Similarly, when assessing these growth factor effects on the CD44+/CD24−/low cancer stem cell population, we found that BMP4 acted as a differentiation factor, able to decrease both basal and TGFβ-induced BCSC numbers." (PMID 33649296, 2021). "Together these results define an antagonistic feedback loop and signaling network between TGFβ superfamily members, whereby TGFβ/Smad/cyclin D1 signaling leads to increased cancer stem cell numbers while BMP4 oppose these effects acting as a potent differentiation factor." (PMID 33649296, 2021). "RT-PCR analysis of β-catGOF; Mll1−/− organoids confirmed a decreased expression of Gata4 and revealed a concomitant upregulation of Bmp4 and the secretory differentiation markers Mmp7 and Muc2, identifying Mll1 as an upstream regulator of Gata4/Bmp4-controlled cancer stemness and differentiation." (PMID 33349639, 2020). "Interestingly, BMP4 stimulates a YAP dependent increase in CDK8 which would also reduce junctional E-cadherin and contribute to cancer associated EMT." (PMID 33057364, 2020). "Here, we show that forkhead box F2 (FOXF2) functions as a master transcription factor for reprogramming cancer cells into an osteomimetic phenotype by pleiotropic transactivation of the BMP4/SMAD1 signaling pathway and bone-related genes that are expressed at early stages of bone differentiation." (PMID 31222004, 2019). "The biological function of BMP4 on cancer cells has also aroused a great deal of controversy." (PMID 30012194, 2018). "Since BMP4 was expressed by C1-type CAFs, we set to determine if the observed decline in frequency of oral stem-like cancer cells and increased proliferation of cells might be through induction of differentiation by BMP4 expressed by C1-type CAFs." (PMID 30287850, 2018). "Within the BMP family, BMP2 and BMP4 have emerged as key regulators of normal and cancer SCs11–13." (PMID 30262802, 2018). "Suppression of BMP4 and CST6 levels in 231_HM.LNm5 cells relative to 231_ATCC cells was retained in 2D culture, suggesting that the mechanism(s) underlying downregulation are cancer cell intrinsic." (PMID 29720474, 2018). "Bone morphogenetic protein 4 (BMP4) plays an important role in cancer pathogenesis." (PMID 28077088, 2017). "Genes associated with the most common VELs included novel genes and several known oncogenes and tumour suppressors implicated in CRC as well as other forms of cancer, including MYC10, 16, BMP4 (refs 17, 18), PHLDA1 (refs 19, 20, 21, 22), SOX9 (refs 23, 24, 25) and TRIB3 (refs 26, 27)." (PMID 28169291, 2017). "Our results showing that EGF induced BMP-4 further suggest the existence of a new functional relationship between both proteins that may be critical in the control of the invasive behavior of cancer cells." (PMID 25897433, 2015). "We find that CHIR99021 and BMP4 significantly decrease the expression of Eras, suggesting these pathways may be candidates for the treatment of some types of human cancer." (PMID 26269429, 2015). "Here, we report that EGF and BMP-4 cooperate to inhibit MMP-9 expression in cancer cells." (PMID 25897433, 2015).
cancer (continued). "Moreover, genes in the WNT, SHH, and BMP pathways such as WNT5A, FZD7, and FZD5, SHH, SMO, and GLI2 as well as BMP4 were likewise among the upregulated genes and were included in pathway of cancer gene set." (PMID 26998479, 2015). "Recently, BMP-4 was shown to affect the response of cancer cells to the antitumor reagents." (PMID 24779016, 2014). "Based on the role of BMP-4 in drug resistance in GC cell lines, we assumed that there might be an association between BMP4 genetic variants and chemotherapy response in cancer patients." (PMID 24779016, 2014). "This study suggests that BMP4 epigenetic and expression status may represent promising biomarkers for cisplatin resistance in cancer cells." (PMID 24779016, 2014). "The prognostic role of BMP-4 in cancer prognosis has been previously reported." (PMID 24779016, 2014). "BMP4 has been reported to induce G1 cell cycle arrest in cancer cells." (PMID 24053318, 2013). "Improved knowledge of the downstream mediators of BMP4 effects in cancer cells may allow dissection of the different BMP4 induced phenotypes and thereby generation of specific targeted therapies." (PMID 23590708, 2013). "A number of cancer molecular markers associated with bone metastasis were assessed by immunohistochemical technique, including PTHrP, OPN, c-Src, MMP2, CXCR4, PI3K, BSP, NFκB, IGF-1R, and BMP4." (PMID 22537906, 2012). "Interestingly, BMP4 has beenfound to be involved in chemotherapeuticagent-induced premature senescence of cancer cells." (PMID 20157553, 2009). "Increasing evidence suggests that Tbx2 and Tbx3 may regulate proliferation in cancer and in development and our data is consistent with a role for these T-box genes downstream of BMP4 in regulating proliferation of the optic cup." (PMID 17173667, 2006). "Thus, BMP4, a factor specifically enriched in the cancer cells and CSCs of PAAD, could serve as a potential prognostic marker for PAAD." (PMID 41169612, 2025). "We therefore proposed that the anti-metastatic activity of BMP4 could be mediated by SMAD4-dependent canonical signalling, and upon the loss of functional SMAD4, BMP4 could promote cancer progression through non-canonical signalling pathways." (PMID 38689334, 2024). "Interestingly, the anti-metastatic effect of BMP4 is retained in immunodeficient mice, indicating the involvement of additional immune-independent mechanisms, such as cell cycle arrest or the induction of anoikis in cancer cells." (PMID 38689334, 2024). "Furthermore, EGF and BMP-4 cooperate to inhibit MMP-9 expression in cancer cells." (PMID 35150338, 2022). "Thus, cancer cell-derived EVs could upregulate BMP4 expression by suppressing Smad9 expression in NSCLC cells." (PMID 33472665, 2021). "In addition, Bmp4-KD suppressed cancer cell migration and invasion in Boyden chamber assays." (PMID 26395571, 2015). "Therefore, the tissue specificity of major regulators and effectors of BMP4 may contribute to its cancer type–specific functions." (PMID 26395571, 2015). "A recent study also showed that BMP4 induces the expression of multiple MMPs, including MMP3 and MMP14, in mouse mammary fibroblasts and it also modestly induces the expression of MMP3 in cancer associated human mammary fibroblasts and to a greater degree in normal human mammary fibroblasts." (PMID 24053318, 2013). "We found BMP4 to be low in normal pancreas but aberrantly upregulated in PAAD, particularly in cancer cells and CSCs, consistent with its origins in stem cell populations." (PMID 41169612, 2025). "As we have shown that BMP4 was initially low expressed in normal pancreas tissues and became the top expressed in PAAD among all cancer types, we determined to systematically study the function and prognostic values of BMP4 in PAAD." (PMID 41169612, 2025). "Previous studies have demonstrated the essential roles of BMP4 and the BMP signaling pathway in the development and certain cancer types." (PMID 41169612, 2025).
cancer (continued). "Overall, the candidate gene set was significantly enriched for known cancer census genes (e.g. SGK1, MECOM, PRKCB) and known transcription co/factors (e.g. CACNA2D3, BMP4)." (PMID 36624125, 2023). "CAF-D (CD44+ CD90+ α-SMAhigh/BMP4 low) synthesized TGF-β1 that are essential for cancer invasion, whereas CAF-N (CD44+ CD90+ α-SMAlow/BMP4 high) included intrinsically motile fibroblasts." (PMID 37024932, 2023). "One study demonstrated that bone morphogenetic protein 4 (BMP-4) activates the Notch signaling pathway via a Smad4-dependent manner in MCF-10 cells, thereby promoting the EMT and advancing the cancer stem cell properties." (PMID 35805056, 2022). "In particular, the population of CAFs secretingBone Morphogenetic Protein 4 (BMP4) and expressingα-SMA inhibited the proliferation of cancer stem cells (CSC)." (PMID 35342854, 2022). "One factor that has been shown recently to be overexpressed in cancers, including GBM, is the secreted BMP4 antagonist CHRDL1." (PMID 36497175, 2022). "Finally, using normal mammary epithelial 3D cell culture assay, we also showed that BMP4 acts as a differentiation factor in normal cells and can induce the formation of 3D acinar structures, further broadening its role as a differentiation factor in normal and cancer cells." (PMID 33649296, 2021). "OC-X treatments also caused surge upregulation of several important biomarkers within each cancer progression stage, including UCP1, NOSTRIN, SCGB3A1, ENG, EPAS1, SFTPD, and BMP4." (PMID 34069906, 2021). "We also noticed that growth factors, including NOV, BMP4, MDK, GDF15, VEGFC, NTF3, and LIF, were previously reported to promote cancer development, especially in cancer metastasis in various cancers, including CRC." (PMID 34440086, 2021). "BMPs belong to the TGFβ superfamily, and BMP4-dependent SMAD1/5/9 signaling is known to have a role in vascular calcifications and various cancers." (PMID 34944071, 2021). "BMP4 treatment had a repressive effect on the MYCN-activated members of the MYCN157 signature and also negatively regulated pediatric cancer markers." (PMID 32210188, 2020). "In cancer, the Hedgehog molecule SMO interacts directly or indirectly with several molecules, including MMPs, BMP4, Rho, CCN1, etc.." (PMID 32962123, 2020). "Taken together, these results suggest that BMP-4 enhances tumorigenesis in MDA-MB-231 cells, as well as its cancer stem cell properties, via Notch activation." (PMID 31409851, 2019). "In the same work, authors demonstrated that BMP4 and BMP7 were upregulated in patients with cirrhosis, HCC and cholangiocarcinoma and the increase correlated with the progression of cancer." (PMID 29295498, 2017). "It should be noted that two cancer markers, CD44 and Bone Morphogenic Protein 4 (BMP4), were differentially found in the three sets of Caco-2 differentiated datasets and absent in normal cells." (PMID 28726765, 2017). "More intensive efforts will be required to elucidate the relationship between BMP4 and MYH10 and to clarify the roles of MYH10 in cancer progression." (PMID 26395571, 2015). "In the present study, we showed that miR-200 suppresses BMP4 indirectly through the GATA4 and GATA6 transcription factors and that BMP4 knockdown inhibits cancer cell growth, migration, invasion, and metastasis." (PMID 26395571, 2015). "When queried for the three most common BMP ligands: BMP2, 4 and 7, we observe that basal cancers have upregulation of BMP2 and BMP7 and downregulation of BMP4." (PMID 26274893, 2015). "BMP4’s known role in promoting differentiation and anti-proliferative effects in GBM CSCs35,36 and its reciprocal inhibition with TGFβ1 in other cancer types may explain this inverse regulation." (PMID 40894044, 2025). "These conflicting observations indicate that not all patients with advanced cancer would benefit from a BMP4-activating therapy, highlighting the need for a deeper understanding of the anti-metastatic actions of BMP4." (PMID 38689334, 2024).
cancer (continued). "Also, other active proteins such as Gremlin-1 (GREM1), bone morphogenetic protein 4 (BMP4), TGF-β, MT-MMPs, laminin-5, integrin, and EGFR promote cancer cell migration and invasion and EMT." (PMID 39120301, 2024). "For this reason, we stimulated EMTimage with BMP4 or BMP7 during the 4‐day period, in order to evaluate two different members of the BMP family that have distinct biological effects in development and in cancer." (PMID 35348275, 2022). "For example, TNF-related apoptosis-inducing ligand (TRAIL), nanoparticles, bone morphogenetic protein 4 (BMP4) and other molecules that can limit cancer cell development were used for modifying MSCs, which reduced cancer cell growth and metastasis while also causing apoptosis." (PMID 34736460, 2021). "BMP4 (bone morphogenetic protein 4) was differentially expressed between the two CAF populations and was suggested to be at least partially responsible for exerting the suppressive effect on cancer cells' stemness." (PMID 35048030, 2021). "BMP4, one BMP family member, is upregulated in several cancers." (PMID 32201526, 2020). "It is noteworthy that HIF1α and BMP4 have both been reported not only to promote MUC5AC expression, but also to upregulate expression of OCT4, which is a pluripotency gene and a marker for lung and cancer stem cells." (PMID 33015064, 2020). "We next aimed to investigate the effects of the elevated levels of circulating BMP4 on bone alone, without influence from the cancer cells." (PMID 31956851, 2020). "In addition, the expression of Jagged-1 significantly correlated with the expression of BMP-4, EMT markers such as Slug, and cancer stem cell makers including ALDH and CD44." (PMID 31409851, 2019). "For example, cancer cell quiescence in the lung is mediated by thrombospondin 1 (TSP1) and bone morphogenetic protein 4 (BMP4), whereas in the bone marrow, TSP1, BMP7, transforming growth factor β2 (TGFβ2), and growth arrest-specific 6 (GAS6) induce and maintain quiescence." (PMID 31623163, 2019). "BMP4 is also an important regulator of cell migration and invasion and is known to induce the epithelial mesenchymal transition (EMT), which grants mobility to cancer cells and eventually aid in metastasis." (PMID 30079292, 2018). "Based on these results, the expression of ITGA2, BMP4 and PLCB1 may contribute to cancer development." (PMID 28947976, 2017). "Given the reported variable response of individual cancer cell lines to BMP stimulation 8, 14, 15, 16, we attempted to predict the migratory capacity of individual cancer cell lines before testing the effect of BMP4." (PMID 28299802, 2017). "Furthermore, we found BMP4 to potently inhibit tumorsphere formation and to reduce the CD44+/CD24− cancer stem cell population in TNBC cells." (PMID 27759034, 2016). "In addition, BMP-2, BMP-4, and BMP-7 are frequently overexpressed in various cancers including breast and prostate." (PMID 22514712, 2012). "We determined that gremlin-1 strongly bound BMP-2 and BMP-4 but this binding did not affect its interaction with cancer cells." (PMID 22514712, 2012). "Gremlin-1 binding to cancer cells was unaffected by the presence of BMP-2, BMP-4, and BMP-7." (PMID 22514712, 2012). "However, a systematic study on the profile and prognostic values of BMP4 from a pan-cancer perspective was still lacking." (PMID 41169612, 2025). "Discrepancies in the consequences of BMP4 signalling may be explained by the status of the canonical and non-canonical signalling pathways in different cancer types." (PMID 38689334, 2024). "Interestingly, enforced expression of BMP4 resulted in a trend of increased AKT1 phosphorylation in both SMAD4-expressing and SMAD4-knockdown cells, consistent with previous reports of a similar effect by BMP2 in other cancers." (PMID 38689334, 2024).
cancer (continued). "It is important to note that for human cancer, we do not have phosphorylation data concerning Smad and that the increase in mRNA expression, while indicative, is not a direct indicator of an increase in BMP4 signaling." (PMID 37766964, 2023). "Thus, we speculated that reduced expression of miR-744 in cancer cell-derived EVs enhanced SUV39H1, which further suppressed the expression of Smad9 and consequently elevated the BMP4 expression, promoting the NSCLC progression." (PMID 33472665, 2021). "Another mechanism to generate cancer stem cells could emerge from a “reprograming” process and results from a continuous exposure of mature cells to BMP2 and BMP4." (PMID 35047500, 2021). "Together with our finding in niche model that MGP may constitute a specific malignant microenvironment concomitant with the induction of BMP-4 in mesenchymal cells, MGP might be regarded more broadly as a niche factor that modifies microenvironments to suit cancer stem cells for survival and growth." (PMID 32322728, 2020). "Secondly, we did not detect the BMP4 expression in either serum or cancer tissue of NSCLC subjects." (PMID 24779016, 2014). "In summary, through data analysis, imaging and functional assays in in vitro and in vivo preclinical models, we demonstrated the anti-cancer effects and feasibility of selectively targeting BMP2/4 in SMAD4 negative EAC by novel anti BMP4 and BMP2/4 VHHs." (PMID 35902550, 2022). "Through this method, we found that BMP4 is among the up-regulated proteins present in conditioned media obtained from 344SQ cells; however, we could not determine how BMP4 is enriched in mesenchymal cancer cells, nor whether BMP4 influences tumorigenesis and metastasis." (PMID 26395571, 2015). "Immunohistochemistry revealed that cancer cells were positive for cytokeratins and vimentin to a varying degree and negative for Desmin, S-100, Osteopontin, BMP-2 or BMP-4." (PMID 19040765, 2008). "In addition, several of these genes have not previously been reported as methylated in any type of cancer (KCNK4, SEPT5, PENK, BMP4, TAL1, PGF, SMARCB1 (INI1), FRZB (SFRP3), IRAK3 and MCM2)." (PMID 19493342, 2009). "The discrepancies in BMP4’s roles in cancer progression may result from a lack of appropriate signaling networks or tissue-specific operation of transcriptional machineries, such as the GATA family of transcription factors, which control BMP4 expression, as confirmed here." (PMID 26395571, 2015).